CYP1A1 (cytochrome P450 family 1 subfamily A member 1)
Diseases named in the same sentence as CYP1A1 in open-access papers (continued):
Sharing a sentence is not in itself a finding about the gene and the disease.
tumor (105 papers, 2003 to 2026). "This research reveals a novel mechanism underlying the function of CYP1A1 as a tumor enhancer and provides additional evidence linking I462V A-to-I RNA editing events to tumor development." (PMID 40175891, 2025). "As CYP1A1 is a key regulator involved in BaP metabolism and has been proven to be highly expressed in tumor samples, we next examined the expression of CYP1A1 among the four subgroups to evaluate their associations with air pollution." (PMID 39432560, 2024). "While various tumor-associated mRNAs were upregulated, expression of the cytochrome P450 family member CYP1A1 was markedly attenuated." (PMID 30615637, 2019). "Pollutants, including PCBs, have been associated with the induction of neoplasms through AhR and cytochrome P450-1A1 (CYP1A1) regulation." (PMID 26752525, 2016). "Our results showed that CYP1A1 A4889G and T6235C polymorphisms alter the risk and clinical or tumor characteristics of BC among a heterogeneous population from Southeastern Brazil." (PMID 26598080, 2015). "Partial and localized loss of CYP1A1 expression was observed in the tumor carrying this risk-variant." (PMID 26517685, 2015). "The estrogen degrading protein CYP1A1 showed localized loss of expression in the tumor carrying CYP1A1:(p.Cys457*)." (PMID 26517685, 2015). "We studied the association between tumor pathology and the expression profile of seven phase I and II drug metabolizing genes (CYP1A1, CYP1B1, ALDH3A1, AOX1, GSTP1, GSTT1 and GSTM3) and some of their proteins." (PMID 26580399, 2015). "Furthermore, we observed a positive association between higher CYP1A1 editing levels and more advanced tumor stage." (PMID 40175891, 2025). "Several of the genes differentially regulated are associated with tumor initiation (e.g., AhR, CYP1A1, CYP1A2, MDM2, EGR1, NFKBIZ), further suggesting that genomic outcomes of short-term exposure truly reflect the longer-term process of malignant transformation." (PMID 25058030, 2014). "Efforts are underway to identify the binding region of the interaction between CYP1A1 and HO-1 to fully understand its role in tumor progression in our future study." (PMID 40175891, 2025). "P.g. also manipulates inflammatory signaling in SCC-25 cells by activating NF-κB and MAPK pathways, driving tumor-associated inflammation and metastasis via upregulation of CCL20, TNFAIP6, CXCL8, TNFAIP3, TRAF5, CYP1A1, and NOD2 gene expression." (PMID 40924302, 2025). "Accordingly, our results demonstrated significantly higher protein expression of CYP1A1 in tumor samples compared to normal samples." (PMID 39432560, 2024). "Correlation analysis of the expression of CCL5, CCR5, and CYP1A1 in tumor tissues after combination therapy revealed a certain degree of correlation among them." (PMID 39183447, 2024). "We analyzed RNA‐seq data from 371 HCC patients in the TCGA database and found that as the pathological grades increased (i.e., the degrees of differentiation decreased), the expression of CYP1A1 in tumor tissue decreased." (PMID 39183447, 2024). "The IHC results showed upregulated expression of CCL5, CCR5, and CYP1A1 in tumor samples from patients following combination therapy." (PMID 39183447, 2024). "Tissue experiments showed that after combination therapy, the CCL5/CCR5/CYP1A1 pathway was activated, which can benefit the residual tumor cells to survive treatment." (PMID 39183447, 2024). "CYP1A1 is a major enzyme that plays a role in carcinogenesis and tumor progression by inducing AhR by binding environmental pollutants such as B[a]P and inhaling chemicals that mitigate their biological and toxic effects." (PMID 38276538, 2024).
tumor (continued). "CCL5 was mainly expressed in the tertiary lymphoid structure (TLS), whereas CYP1A1 was predominantly expressed in the remaining active tumor cells, especially those adjacent to TLS." (PMID 39183447, 2024). "After IHC was conducted on the liver and tumor tissue of mice, we found that the expression of CYP1A1 in tumor tissue increased significantly after treatment, while the change in the liver tissue was not obvious." (PMID 39183447, 2024). "From the images, we can see that CYP1A1 was predominantly expressed in tumor cells, while other cells barely expressed it." (PMID 39183447, 2024). "IHC and mIHC further exhibited the increased infiltration of CD8+CCL5+ T cells after treatment, leading to an upregulated expression of CYP1A1 in residual tumor cells." (PMID 39183447, 2024). "After analyzing the CYP1A1 expression in residual tumor cells, we found that the proportion of CYP1A1 positively stained tumor cells increased considerably after treatment." (PMID 39183447, 2024). "Ultimately, animal experiments were undertaken to clarify the alterations in CYP1A1 expression within the liver or tumor tissues following the administration of anti‐PD1 antibody or/and lenvatinib." (PMID 39183447, 2024). "The mRNA expression of CCL5, CCR5, and CYP1A1 in tumor specimens from surgery after combination therapy was significantly higher than that in tumor tissues from direct surgery." (PMID 39183447, 2024). "Contribution of signatures in each cohort is provided on the right; (j–k) Protein abundance of CYP1A1 (j) and AhR (k) in tumor and normal samples within the XWLC cohort; Two-tailed Wilcoxon rank sum test used to calculate p-values in (j–k)." (PMID 39432560, 2024). "This phenomenon, combined with the heterogeneity of CYP1A1 expression in tumors mentioned previously, indicates the active metabolic reprogramming in tumor tissue, particularly during combination therapy." (PMID 39183447, 2024). "This tumor-suppressing role of CYP1A1 and CYP1B1 was supported by patient data which demonstrated an association between reduced target gene expression and worse overall survival." (PMID 37958428, 2023). "In TMA, the expression of CYP1A1 was weak in normal tissues and moderate in primary and metastatic tumours." (PMID 34556703, 2021). "The expression of CYP1A1, 1B1 and 2W1 was measured in primary tumours from snap-frozen human HNC tissues and tissue microarray (TMA)." (PMID 34556703, 2021). "Expression of CYP1A1 has been found to be high in breast tumour cells with a positive correlation to tumour grade and menopausal status in newly diagnosed patients with adenocarcinoma of the breast." (PMID 33809117, 2021). "This supports the potential for CYP-activated prodrugs for therapeutic intervention in HNC following patient profiling for tumour CYP1A1, 1B1 or 2W1 expression." (PMID 34556703, 2021). "CYP1A1 was undetectable in normal and tumor samples, whereas CYP1B1 expression was significantly higher in PTC than in normal thyroid with median difference of 1.27 (range 0.10–20.87, p = 0.0004)." (PMID 31936153, 2020). "Here, using GEO datasets, we showed that the expression of CYP1A1, CYP1A2, and CYP1B1 was associated with grade, stage, and tumor progression in BC patients." (PMID 32907554, 2020). "In mice‐bearing 5F 203‐sensitive MKN‐45 and 5F 203‐insensitive BGC‐823 tumours in opposite flanks, CYP1A1, CYP2W1 and γH2AX protein in MKN‐45 tumours only following treatment of mice with 5F 203 (5 mg/kg) revealed PD biomarkers of sensitivity." (PMID 31876059, 2020). "Taken together, the observation that MΦs repress CYP1A1 expression in tumor cells and enhance their proliferation, nicely corroborates clinical data." (PMID 30615637, 2019). "The role of CYP1A1 in tumor development appears to depend both on the cell type expressing CYP1A1 as well as on the exact conditions." (PMID 30615637, 2019). "Reduced CYP1A1 mRNA expression (50%) in tumor spheroids after MФ infiltration was further verified using qPCR analyses." (PMID 30615637, 2019).
tumor (continued). "Taken together, these data suggest that MФs, irrespective of their polarization or activation status, release factors which attenuate the expression of CYP1A1 in the tumor cells." (PMID 30615637, 2019). "CYP1A1 mRNA expression was down-regulated in tumor cells upon exposure to MΦ-derived factors in a contact-independent manner." (PMID 30615637, 2019). "While most mRNAs showed elevated expression in tumor cells upon MФ infiltration, CYP1A1 mRNA expression was down-regulated more than 2.08 fold (Log2FC = -1.06)." (PMID 30615637, 2019). "As a side note, CYP1A1 was expressed at a higher basal level in tumor spheroids as compared to monolayer tumor cells, yet equally down-regulated by MΦs in both settings." (PMID 30615637, 2019). "Supernatants from MФs co-cultured with MCF7 cells, which display a tumor-associated MΦ (TAM)-like phenotype, inhibited CYP1A1 expression as compared to supernatants of MCF7 cells." (PMID 30615637, 2019). "Since CYP1A1 acts not only as an activator of carcinogens, but also can activate certain pro-drugs, a detailed understanding of its expression within the tumor microenvironment appears of great interest." (PMID 30615637, 2019). "With respect to molecular changes, we observed that while the expression of the majority of mRNAs increased in the tumor cells upon MΦ infiltration, CYP1A1 expression appeared to be inhibited." (PMID 30615637, 2019). "Intriguingly, only tumor xenografts whose growth were inhibited by 58c demonstrated inducible CYP1A1." (PMID 30208629, 2018). "Since CSCs, as tumor-initiating cells, are major targets for chemical carcinogens, it is highly possible that AhR/CYP1A1 signaling pathway plays a role in controlling CSCs." (PMID 28103884, 2017). "At 5% wt/wt of diet, blueberry appeared more effective in reducing tissue proliferation, tumor burden and down-regulating CYP1A1 expression, while black raspberry delayed tumor latency to a greater extent and down-regulated ERα expression." (PMID 27775562, 2016). "In HepG2 cell culture media, dasatinib is removed by all tumor-expressed CYP with the following clearance rate: CYP2J2>CYP1A1>CYP1B1." (PMID 24819355, 2014). "The mRNA expression of CYP1A1, 1B1, 2J2 and 3A4 in tumor biopsies has shown i) the strong variability of CYP expression and ii) distinct outliers showing high expression levels (esp." (PMID 24819355, 2014). "In this study, we have evaluated the capability of CYP1A1, 1B1 and 2J2, known to be over-expressed in various tumor types and known to biotransform various drugs, to metabolize 5 TKI: dasatinib, imatinib, nilotinib, sunitinib and sorafenib." (PMID 24819355, 2014). "The determination of mRNA expression of CYP1A1, 1B1, 2J2 and 3A4 in tumor biopsies have mainly shown the strong variability of CYP expression with distinct outliers showing high expression levels that are compatible with high intratumoral CYP activity." (PMID 24819355, 2014). "This unique pattern of tumor sensitivity has been attributed to the need for intracellular bioactivation by cytochrome P450 1A1 (CYP1A1) and sulfotransferase 1A1 (SULT1A1) to convert AF to DNA-damaging species." (PMID 24058584, 2013). "Second, the expression levels of CYP1A1 are drastically up-regulated in tumor cells treated with Triflorcas." (PMID 23071625, 2012). "From this point of view, its interaction with CYP3A4 seems mainly related to total-body exposure gefitinib, while CYP1A1 is mainly responsible of its metabolism in tumor cells." (PMID 22111840, 2011). "While non–tumor-derived cells express intermediate CYP1A1 mRNA levels, ERα-positive tumor cells express high levels, and CYP1A1 mRNA expression in ER-negative tumor cells is minimal or negligible." (PMID 22254019, 2010). "The cytochromes P450 CYP1B1 and CYP1A1 are differentially expressed within the tumour microenvironment compared with the surrounding normal tissue and have been proposed as targets for novel chemotherapeutic agents." (PMID 18454852, 2008).
tumor (continued). "Guided by in vitro data and the knowledge that CYP1A1 protein can clearly be detected within sensitive xenografts 24 h post-treatment, tumours were recovered 24 h after animals were treated and DNA extracted." (PMID 12569393, 2003). "Crucially, induction of CYP1A1-catalysed biotransformation of 2-(4-aminophenyl)benzothiazoles within tumour cells is essential for drug activation." (PMID 12569393, 2003). "Functional experiments using FTH1‐knockdown/−overexpressing HCC cell lines and xenograft models demonstrated that FTH1 enhances proliferation, migration, and tumour growth by upregulating CYP1A1/CYP1A2 in the tryptophan pathway, thereby increasing the synthesis of 6‐hydroxymelatonin (6‐HMT)." (PMID 40504108, 2026). "RNA-seq identified robust induction of xenobiotic metabolism (CYP1A1, CYP1B1), oxidative/metabolic stress mediators (GDF15, TIPARP), and tumour-associated genes (FOSB, VGF), alongside repression of tumour suppressors (FAT1, LINC00472)." (PMID 41600570, 2025). "Furthermore, there was a substantial increase in total Akt and phospho-Akt expression level of A549I462V in comparison with A549 control cell, suggesting that CYP1A1 overediting enhanced the tumor progression through PI3K-Akt signaling pathway activation." (PMID 40175891, 2025). "The edited CYP1A1 enhanced the interaction with heme oxygenase-1 (HO-1) and mediated the nuclear translocation of HO-1 to confer resistance to oxidant stress, which promoted cell proliferation and tumor progression in NSCLC." (PMID 40175891, 2025). "Consequently, tumour-associated CYP450 isoforms, such as CYP1A1, CYP1B1, CYP2S1, and CYP2W1—have become a focus for the development of novel anticancer therapies." (PMID 41174467, 2025). "This suggests that the in vivo tumour microenvironment may enhance CYP1A1 stability or metabolic activity, possibly due to stromal interactions or extracellular matrix remodelling." (PMID 41174467, 2025). "Based on these findings, we hypothesized that CCL5 may play a role in levatinib resistance by increasing CYP1A1 expression in tumor cells." (PMID 39183447, 2024). "Our results also suggest that activated AhR may contribute to the tumor–stroma interaction (through CYP1A1 and CYP1B1) in diffuse GC." (PMID 39200369, 2024). "In addition, AhR inhibition by SR1 downregulated Cyp1a1, Cyp1b1 and Runx1 expression in MEPs in tumor-bearing mice." (PMID 37919525, 2023). "However, there were no significant changes in the expression levels of AHR signaling pathway-related molecules, including AhR, AhRR, Cyp1a1, Cyp1a2, Cyp1b1 and Cox2, in tumor-infiltrating neutrophils from Arnt−/− mice." (PMID 36859266, 2023). "Moreover, gypenosides significantly inhibited tumor growth in vivo, and gypenosides significantly reduced cPLA2 and CYP1A1 expression." (PMID 35370678, 2022). "The greater correlation found between CYP1A1 expression and tumor size, and regional metastases reinforce the hypothesis that the more bioactivation and presence of carcinogens, the poorest outcome can be found." (PMID 35409669, 2022). "CYP1 analysis of TCGA-BRCA RNAseq data revealed CYP1A2 expression to be very low (max TPM = 1.3 with a median TPM = 0), while expression of CYP1A1 was high in a subset of tumours (max TPM = 78.3 but median TPM = 0.04) and CYP1B1 was generally more abundant (max TPM = 1611.7 and median TPM = 31.9)." (PMID 33809117, 2021). "However, high expression of CYP1A1 and CYP1A2 was associated with histological grade, tumor stage, and progression." (PMID 32907554, 2020). "CYP1B1 and CYP1A1 may also affect the formation of advanced carcinoma and affect enzymes involved in the metabolism of chemotherapeutic agents that may help prevent tumor cytotoxicity." (PMID 31998435, 2020). "Expression of AhR and CYP1A1 protein in MKN‐45 tumour tissue was analysed by immunohistochemistry." (PMID 31876059, 2020). "Furthermore, CYP1A1 mRNA expression was also reduced in tumor cells grown as monolayers after their co-culture with MФs." (PMID 30615637, 2019).
tumor (continued). "This suggests that CYP1A1 expression might be a biomarker in human tumors for identification of sensitive tumor phenotypes." (PMID 30208629, 2018). "However, a case-controlstudy on Japanese women showed a decreased riskwith homozygous CYP1A1*2A among breast cancerpatients." (PMID 28868835, 2017). "To further substantiate that CYP1A1 is a minor contributor to CYP1 activity noted in tumors we performed incubations of tumor microsomes with diosmetin in the presence of a polyclonal antibody raised against human CYP1A1 purchased from Millipore (AB 1258, Massachusetts, US)." (PMID 24358191, 2013). "Our objective was to define a possible potential role of gefitinib metabolism in early evaluation of tumor response to gefitinib, to analyze conditions or factors that can alter tumor gefitinib metabolism and to test the effect of CYP1A1 inhibition on gefitinib efficacy." (PMID 22111840, 2011). "In addition, cytotoxicity across a large panel of human tumour cell lines correlates with CYP1A1 inducibility." (PMID 12592376, 2003). "Furthermore, overediting of CYP1A1 in tumors was found to be predictive of poor prognosis and associated with tumor recurrence independent of smoking history." (PMID 40175891, 2025). "Moreover, fucoxanthin induces a marked increase in cytochrome P450 1A1 (CYP1A1) expression only in HepG2 cells, which could mean that carotenoids have effects on tumour cells mediated by both common and tumour-specific molecular mechanisms." (PMID 39334719, 2024). "AhR may contribute to the tumor–stroma interaction (through CYP1A1 and CYP1B1) in diffuse GC." (PMID 39200369, 2024). "The increasing expression of CYP1A1 and CYP1B1 is related to the AHR pathway and causes the production of electrophilic derivatives by cytochrome P450 metabolizing enzymes to form DNA adducts, resulting in the activation of oncogenes and inactivation of tumor suppressor genes." (PMID 34784845, 2021). "Furthermore, CYP1A1 protein was induced in the tumour tissues of mice after 5F 203 treatment." (PMID 31876059, 2020). "Although the majority of the studies have focused on the carcinogenic action of CYP1A1, it is recently becoming clear that this enzyme plays important roles in detoxication and chemoprevention, thus opposing the initially established concept, regarding its function in tumor progression." (PMID 19531241, 2009). "Compared with control LNCaP xenografts, LM10-treated xenografts also significantly reduced the mRNA levels of TDO2, AhR, CYP1A1 and CYP1B1 in castration-recurrent tumours." (PMID 40759641, 2025). "CYP1A1, another AhR target gene, showed elevated protein levels in two of three late-stage CRC tumours, aligning with earlier studies." (PMID 40348885, 2025). "Tumor‐bearing mouse experiments demonstrated that bergamottin (BGM), a competitive inhibitor of CYP1A1, can enhance the efficacy of both lenvatinib and combination therapy." (PMID 39183447, 2024). "It is also well known that CYP1A1 and CYP1B1 have important roles in tumor development (cell invasion, migration, and disease progression), in part linked to their metabolic activation by BaP." (PMID 39200369, 2024). "CYP1A1 and CYP1B1 have a central role in tumor development and the activation step of pro-carcinogen compounds such as BaP." (PMID 39200369, 2024). "The expression of both Cyp1a1 and Cyp1b1 was upregulated in MEPs isolated from MC38 or E0771 tumor-bearing mice compared to in control healthy mice." (PMID 37919525, 2023). "Considering the whole sample, Spearman’s correlation coefficient showed significant correlations between tumor size and duration of tobacco use (p = 0.036), AUDIT score (p = 0.001), and CYP1A1 expression (p = 0.002)." (PMID 35409669, 2022). "circFLNA overexpression has been found to promote tumor growth, inhibit miR-486-3p expression and promote the expressions of XRCC1 and CYP1A1, however, miR-486-3p mimic led to the opposite effect of overexpressed circFLNA." (PMID 33500536, 2022).